SP1 (Sp1 transcription factor)
Diseases named in the same sentence as SP1 in open-access papers (continued):
Sharing a sentence is not in itself a finding about the gene and the disease.
astrocytoma (3 papers, 2016 to 2022). "Other studies inferred that Sp1 may drive CXCL12 expression in human astrocytoma cells, human lung fibroblasts, and rat β-cells." (PMID 36670936, 2022).
astroglioma (3 papers, 2013 to 2017). "The Sp1 binding site is essential for basal transcriptional activity of both MMPs as only ∼10% and ∼30% of transcription activity is observed when Sp1 at −102 on MT1-MMP in human fibrosarcoma HT-1080 and at −91 on MMP-2 in astroglioma cells is mutated respectively." (PMID 23967226, 2013).
atrial fibrillation (3 papers, 2019 to 2024). A disorder characterized by an electrocardiographic finding of a supraventricular arrhythmia characterized by the replacement of consistent P waves by rapid oscillations or fibrillatory waves that vary in size, shape and timing and are accompanied by an irregular ventricular response. "LncRNA PVT1 promotes atrial fibrosis via miR-128-3p-SP1-TGF-β1-Smad axis in atrial fibrillation." (PMID 30894138, 2019). "Finally, the changes in the natriuretic peptide system, which play a diuretic role in atrial fibrillation, require further study for confirmation.Finally, Sp1 has been reported upregulated in glomerulonephritis and is an important transcriptional mediator of TGF-β signaling." (PMID 36899056, 2023). "Studies have indicated that SP1 plays a role in regulating the development of long QT syndrome (LQTS), ventricular arrhythmias, and atrial fibrillation (AF)." (PMID 39062521, 2024).
autism (3 papers, 2016 to 2023). Persistent deficits in social interaction and communication and interaction as well as a markedly restricted repertoire of activity and interest as well as repetitive patterns of behavior. "SP1 is known to regulate several autism candidate genes, and its biological importance to ASD is underscored by the fact that SP1 proteins are markedly elevated in the anterior cingulate gyrus (ACG) of autistic patients." (PMID 37761876, 2023). "Elevated expression of Sp1 has been observed in the brains of autism patients, along with altered expression of a number of ASD candidate genes that have Sp1 binding sites, including reelin (RELN)." (PMID 33327933, 2020). "Elevated levels of Sp1 have been found in the frontal lobes of deceased patients with AD74; Sp1 has been associated with neuroinflammation in AD and other diseases such as autism." (PMID 27212113, 2016). "Excessive Sp1 in FXS, autism, and AD implicates inflammatory reactions, which have been associated with each of these conditions." (PMID 27212113, 2016).
cardiomyopathy (3 papers, 2019 to 2024). A disease of the heart muscle or myocardium proper. "This review focuses on the involvement of SP1 in various cardiac diseases, including coronary heart disease, ischemia-reperfusion injury, cardiomyopathy, arrhythmia, and vascular disease." (PMID 39062521, 2024).
chondrosarcoma (3 papers, 2013 to 2021). A malignant cartilaginous matrix-producing mesenchymal neoplasm arising from the bone and soft tissue. "In summary, our study revealed that the expression of SNHG6 was upregulated in chondrosarcoma, which was induced by SP1 activation." (PMID 33431838, 2021). "To ascertain the association among KLF6, EZH2, SP1, and SNHG6 during the progression of chondrosarcoma, we then measured the expression of EZH2 and SP1 in KLF6-overexpressing SW1353 and HCS2/8 cells." (PMID 33431838, 2021). "Our study showed that SNHG6 expression was upregulated in chondrosarcoma tissues and cell lines, which was induced by SP1 activation." (PMID 33431838, 2021). "The current study demonstrated that BDNF increases MMP-1 expression by binding to the TrkB receptor and activating the ASK1, JNK/p38, and Sp1-dependent pathways, thereby enhancing the migration and invasion activity of human chondrosarcoma cells." (PMID 23892595, 2013). "In the present study, we for the first time found that SP1 induced the upregulation of SNHG6, which then led to the suppression of KLF6 by recruiting EZH2 and promoted the tumorigenesis of chondrosarcoma." (PMID 33431838, 2021). "Our results indicate that BDNF enhances the migration and invasion activity of chondrosarcoma cells by increasing MMP-1 expression through a signal transduction pathway that involves the TrkB receptor, ASK1, JNK/p38, and Sp1." (PMID 23892595, 2013). "The results showed that BDNF binds to TrkB, which activates the ASK1, JNK/p38, and Sp1 pathways, leading to up-regulated MMP-1 expression, resulting in the promotion of migration of human chondrosarcoma cells." (PMID 23892595, 2013). "In summary, this study reveals that SP1-induced SNHG6 forms a positive loop to facilitate the carcinogenesis of chondrosarcoma through the suppression of KLF6 by recruiting EZH2, which manifests the oncogenic function of SNHG6 in chondrosarcoma." (PMID 33431838, 2021). "Therefore, activation of the TrkB receptor and the ASK1, JNK/p38, and Sp1 pathways are required for BDNF-induced cell migration and MMP-1 production in human chondrosarcoma cells." (PMID 23892595, 2013). "In line with that observed in SW872 cells, the increases in GDF5 expression were not significant following Sp1, Sp3 and P15 depletion but a significant fold change was observed upon DEAF-1 knockdown in this chondrosarcoma cell line." (PMID 23825960, 2013).
chronic lymphocytic leukemia (3 papers, 2018 to 2022). "Other studies established that miR-29b modulated the global DNA methylation through targeting DNMT3A and DNMT1, leading to decreased transcription factor specificity protein 1 (SP1) and increased p21 expression in chronic lymphocytic leukemia (CLL) cells." (PMID 33632341, 2021).
colitis (3 papers, 2015 to 2022). Inflammation of the colon. "Utilizing these findings, in vivo experiments were designed, and the results showed that the colitis caused by CPT-11 was remarkably ameliorated with the inhibition of SP1 or activation of TGR5." (PMID 35712724, 2022). "Treating rats receiving CPT-11 with MitA to inhibit SP1 or OA to activate TGR5 can alleviate the colitis." (PMID 35712724, 2022). "Combining in vitro analyses and a mouse model of colitis, we show that oral administration of recombinant bacteria secreting SP-1 (i) compromises the epithelial barrier, (ii) alters the microbial community, and (ii) exacerbates colitis." (PMID 34685638, 2021). "To investigate the role of SP-1 during inflammation, we experimentally induced mild colonic inflammation through oral DSS administration along with L. lactis secreting SP-1 or PBS." (PMID 34685638, 2021). "In summary, this study has (i) reported the functional characterization of a newly identified serine protease from a dysbiotic gut bacterium, and (ii) shown that SP-1 is able to exert potential pro-inflammatory responses during colitis and exacerbate inflammation." (PMID 34685638, 2021). "MitA significantly inhibited SP1 and p-SP1 and ameliorated inflammation, while OA inhibited NLRP3 inflammasome and ameliorated colitis through promoting TGR5." (PMID 35712724, 2022). "Administered SP-1 increased epithelial permeability, dysregulated the gut microbiota, and worsened inflammation in the dextran sodium sulfate (DSS) mouse model of colitis." (PMID 34685638, 2021).
cystic fibrosis (3 papers, 2008 to 2023). Autosomal recessive disorder caused by pathogenic variants in the CFTR gene (cystic fibrosis transmembrane conductance regulator), which encodes a chloride and bicarbonate channel expressed in epithelial cells, and follow the diagnosis criteria. "In human cystic fibrosis bronchial epithelial cells, curcumin lowers the nuclear expression of transcriptional stimulatory protein 1 (SP1), which is among the critical reasons for the enhanced production of basic TLR2." (PMID 37110167, 2023). "However, Sp1 has been shown to act as a critical component of the DNA demethylation-dependent upregulation of TLR2 expression in cystic fibrosis epithelial cells." (PMID 26223836, 2015).
disc degeneration (3 papers, 2021 to 2025). "Sp1 polymorphism was correlated with increased risk of disc degeneration under allelic model (T vs. G: OR = 1.28, 95% CI 1.00–1.64, P = 0.047), recessive model (TT vs. GG + GT: OR = 3.66, 95% CI 1.96–6.85, P < 0.001), and homozygote model (TT vs. GG: OR = 3.40, 95% CI 1.80–6.40, P < 0.001)." (PMID 34663366, 2021). "Our analysis showed that COL1A1 Sp1 polymorphism was also associated with susceptibility to IVDD and TT genotype conferred more than threefold risk to disc degeneration than GG genotype." (PMID 34663366, 2021). "In severe disc degeneration, RCOR2, STAT3, NOTCH1, SP1, and SART1 expression were elevated, while PRIM1 and LYAR expression levels were significantly reduced." (PMID 40799650, 2025).
embryonal carcinoma (3 papers, 2013 to 2021). A non-seminomatous malignant germ cell tumor characterized by the presence of large germ cells with abundant cytoplasm resembling epithelial cells, geographic necrosis, high mitotic activity, and pseudoglandular and pseudopapillary structures formation. "For example, SP1, previously implicated in tumorigenesis and cell cycle regulation, and as a regulator of NANOG expression in murine embryonic carcinoma cells." (PMID 33256189, 2020). "Interaction between PEA3 and Sp1 has been reported in embryonal carcinoma P19 cells and shown to be necessary for upregulating the T gene required for induction of embryonic differentiation." (PMID 23967226, 2013).
fetal growth restriction (3 papers, 2012 to 2025). A fetus that does not grow beyond the 10th percentile of conventionally accepted weight for gestational age. "SP1 has been shown to regulate the placental glucocorticoid barrier by repressing the expression of 11β-hydroxysteroid dehydrogenase type 2, leading to fetal growth restriction (FGR)." (PMID 34867824, 2021). "In rats, intrauterine growth restriction is associated with both reduced HSD11B2 expression and increased HSD11B2 promoter methylation in kidneys at birth and these epigenetic effects lead to altered transcription factor binding of Sp1 and NF-κB." (PMID 22761903, 2012).
gastric tumor (3 papers, 2015 to 2025). "Sp1 has been identified as a direct target of miR-22 in gastric tumors, with an inverse linear correlation between miR-22 expression and Sp1 mRNA." (PMID 41583211, 2025). "Specificity protein 1 (Sp1) expression is regulated by miR-22 and has been recognized as a direct target of Sp1, and an inverse linear correlation between miR-22 and Sp1 mRNA expression has been observed in gastric tumors." (PMID 41583211, 2025).
glomerulonephritis (3 papers, 2023 to 2024). A renal disorder characterized by damage in the glomeruli. "Elevated Sp1 expression is reported in the kidney of patients with glomerulonephritis and podocytes in db/db mice." (PMID 39598328, 2024). "The study earlier reported that SP1 plays a crucial role in the pathogenesis and the progression of human glomerulonephritis probably via cooperation with pSmad2/3 and p30033." (PMID 36878974, 2023).
HCMV infection (3 papers, 2012 to 2022). "Increased expression and activation of NF-κB molecules following HCMV infection have been found to be regulated by different mechanisms, including transactivation by HCMV IE genes such as IE1-72, IE2-86 and IE2-55, and increased DNA binding activity of transcription factor SP1." (PMID 23418456, 2013).
head and neck cancer (3 papers, 2014 to 2025). A primary or metastatic malignant neoplasm affecting the head and neck. "Regulation of epithelial-to-mesenchymal transition (EMT) by YEATS2 is SP1-dependent in head and neck cancer (HNC)." (PMID 40810390, 2025). "We report that the histone reader YEATS2 is responsible for increased invasive potential in head and neck cancer in an SP1-dependent manner." (PMID 40810390, 2025). "HDAC6 and SP1 interaction has neither been demonstrated in head and neck cancers nor radiation resistant cancers." (PMID 39800760, 2025).
head and neck squamous cell carcinoma (3 papers, 2012 to 2021). A squamous cell carcinoma that arises from any of the following anatomic sites: lip and oral cavity, nasal cavity, paranasal sinuses, pharynx, larynx, and salivary glands. "Our data suggested the oncogenic role of transcriptional factors SP1 and miR-92b, and highlighted a potential treatment targeting SP1/miR-92b in head and neck squamous cell carcinoma patients." (PMID 34905435, 2021). "Therefore, we evaluated how the NAB2-mediated suppression of EGR1 facilitates head and neck squamous cell carcinoma (HNSCC) cancer progression, in association with Sp1, which competes with EGR1 as a transcriptional regulator." (PMID 30845713, 2019). "In this study we report a novel specificity protein 1 (SP1)/microRNA-92b (miR-92b) feedback loop regulating the migration and invasion of head and neck squamous cell carcinoma (HNSCC)." (PMID 34905435, 2021).
hypospadias (3 papers, 2018 to 2020). Hypospadias is the displacement of the urethral meatus on the ventrum of the penis. "We identified rs11170516 with the risk allele G within the SP1/SP7 region that was independently associated with moderate-severe hypospadias [SP1/SP7, rs11170516, Pcombine = 3.5 × 10− 9, odds ratio (OR) = 1.96 (1.59–2.44)]." (PMID 31856834, 2019). "Although we think that the association between the variant and hypospadias is mediated via SP1, it could also be another mechanism." (PMID 31856834, 2019). "To further interpret the potential mechanism regulated by SP1 and SP7, we investigated these two genes and previous reported hypospadias risk associated genes by PPIs analysis using GeneSense and STRING." (PMID 31856834, 2019). "We performed the first GWAS of moderate-severe hypospadias in a Han Chinese cohort, and identified one novel susceptibility cis-acting regulatory locus at 12q13.13, which may regulate a variety of hypospadias-related pathways by affecting proximal SP1 gene expression and subsequent PPIs." (PMID 31856834, 2019). "So if SP1 or SP7 interacts with one of the proteins encoded by a hypospadias risk gene, it is likely to interact (indirectly) with many of the proteins encoded by hypospadias risk genes." (PMID 31856834, 2019). "Although we did not include all possible proteins encoded by hypospadias risk associated genes (for example IRX5, IRX6, EYA1) for PPIs, our investigations indicated that disruption of SP1 and SP7 activity is associated with multiple known hypospadias risk associated genes in human via PPIs." (PMID 31856834, 2019). "Furthermore, a significantly negative correlation was detected between the mRNA expression levels of the CYP1 family genes and the methylation level of the − 221 Sp1 site of SRD5A2 in hypospadias." (PMID 29080015, 2018). "In summary, we conducted the first GWAS of moderate-severe hypospadias in a Han Chinese cohort and identified one new susceptibility locus (rs11170516) at 12q13.13, which may regulate a variety of hypospadias-related pathways by affecting proximal SP1 gene expression." (PMID 31856834, 2019). "A significantly negative correlation was detected between the mRNA expression and methylation levels of SRD5A2 in the hypospadias group particularly at the − 221 Sp1 site, whereas no such negative correlation was detected in the phimosis group." (PMID 29080015, 2018). "Negative correlations were found between the methylation level of SRD5A2, especially at the − 221 Sp1 site, and the CYP1 family mRNA expression levels (CYP1A1, p = 0.002; CYP1B1, p = 0.007) in hypospadias patients, but not in phimosis patients." (PMID 29080015, 2018).
ovarian clear cell cancer (3 papers, 2014 to 2015). An invasive malignant neoplasm that arises from the ovary and is characterized by a predominance of clear and hobnail malignant epithelial cells. "We previously demonstrated that a physical interaction between the ubiquitously expressed transcription factor Sp1 and HIF2 is a major cause of FVII gene activation in poor prognostic ovarian clear cell carcinoma (CCC) cells under hypoxia." (PMID 25879517, 2015). "In contrast to the abrogated Sp1-HIF-2α interaction in some cell types, direct association between Sp1 and HIF-2α on gene promoters is also possible and activates multiple genes in ovarian clear cell carcinoma (CCC) cells." (PMID 26703734, 2015).
prostate tumor (3 papers, 2012 to 2020). "As expected, the plasmid and transduced SP1-Cas9 cell samples cluster away from the prostate tumours, and tumours cluster by treatment (vehicle or docetaxel)." (PMID 33033111, 2020). "We also compared the expression of AKR1C1, c-FLIP, Sp1, Sp3 and ERβ in human prostate tumors and normal tissue from oncomine, cancer-profiling database." (PMID 25816367, 2015). "The current study for the first time demonstrates elevated expression of Sp1 in human prostate tumors compared to normal tissue." (PMID 25816367, 2015). "Expression of Sp1 and c-FLIP are elevated while AKR1C1, ERβ and Sp3 are significantly low in human prostate tumor samples." (PMID 25816367, 2015). "In silico analysis of these data from two different cohorts revealed significantly upregulated expression of Sp1 and c-FLIP in human prostate tumors compared to normal tissue." (PMID 25816367, 2015). "Subsequent studies showed that inhibition of prostate tumor development in a preclinical animal model was accompanied by down-regulation of FLIP and Sp1." (PMID 23028678, 2012). "IHC analysis revealed significantly elevated Sp1 expression (27/35 human prostate tumors; p = 0.035) with no detectable expression in the normal tissue." (PMID 25816367, 2015). "Furthermore, we also showed that FLIP is regulated transcriptionally through modulation of the transcription factors Sp1 and Sp3 and that inhibition of FLIP prevented prostate tumor development in a preclinical animal model." (PMID 23028678, 2012). "However, to the best of our knowledge no studies have examined the expression of Sp1 and Sp3 in human prostate tumors." (PMID 25816367, 2015).
Sjogren syndrome (3 papers, 2015 to 2019). An autoimmune disorder in which immune cells attack and destroy the glands that produce tears and saliva. "The current studies demonstrate that many patients with idiopathic dry eyes with or with out dry mouth have markers for early Sjogren’s syndrome, anti-SP1, anti-CA6 and anti-PSP." (PMID 28270126, 2017). "To elucidate the role of the tissue-specific autoantibodies (TSAs), i.e., anti-CA6, anti-SP1, and anti-PSP antibodies, we enrolled 137 pSS patients, 32 secondary Sjögren's syndrome (sSS) patients, and 127 healthy controls (HCs), whose serum and saliva samples were collected." (PMID 31205955, 2019).